CD44 (CD44 molecule (IN blood group))
Diseases named in the same sentence as CD44 in open-access papers (continued):
Sharing a sentence is not in itself a finding about the gene and the disease.
cancer (continued). "A removal of the moieties, e.g. by site directed mutagenesis, transfers CD44 into the non-raft domains which is in agreement with the organization in invasive cancer cells." (PMID 32271757, 2020). "Studies targeting CD44 are in different preclinical and clinical stages for some cancer types, but are still lacking for STS." (PMID 32532153, 2020). "However, both high CD44 expression and STAT3 activation in CAFs have been reported to maintain CSC phenotype and promote cancer drug resistance in other cancer types." (PMID 33335857, 2020). "Basically, while CD44 recruits MMP-9 at the protrusions of migrating cells, thereby spatially directing MMP-9 proteolytic activity, CD151 facilitates MMP-9-mediated cancer cell motility by mediating integrin endocytosis at the rear or basal-lateral front of migrating cells." (PMID 32630531, 2020). "Even though the levels of CD44 and HA can be increased in several types of malignant tumors, in some cancers, its levels are not a consistent indicator of unfavorable prognosis." (PMID 32610620, 2020). "CSCs drive cancer initiation, progression, metastasis, recurrence and drug resistance, and express Nanog, CD133, CD90, SOX2, EpCAM, CD44, Klf4 and Oct4, some of which may functionally support liver CSC phenotypes like invasiveness and chemoresistance." (PMID 33343368, 2020). "The increased CD44 expression in PMCs promote cancer invasion by inducing PMCs to secrete matrix metalloproteinase (MMP) 9 and by destroying the mesothelial barrier for improved cancer cell invasion." (PMID 32230983, 2020). "Compared with control xenograft tumors, the mRNA levels of cancer stemness-related genes, including ABCG2, BMI1, NANOG, KLF4, and OCT4 were increased and the protein expression of ABCG2, Oct4, Bmi-1, and CD44 were also increased in HBx-expressing xenograft tumors." (PMID 32168902, 2020). "In addition, a list of known JUN-target genes, including MMP3, CD44, EGFR, ENPP246, and MGST147, were markedly upregulated in cancer cells with SH3RF3 overexpression." (PMID 32427938, 2020). "Consistent to this result, the percentages of CD133+ and CD44+ cells were found to decrease with the knockdown of FAM83C-AS1 in RKO and SW620 cells marked with CD133+ or CD44+, indicating that downregulation of FAM83C-AS1 blocks the cancer stemness." (PMID 33109776, 2020). "Responses to either ICG-001 or DAPT did not correlate with the pathological stage or grade of the cancer or percentage of CXCR4+MET+CD44+ cells indicating that specific mechanisms of response exist." (PMID 32066735, 2020). "Moreover, OPN can directly interact with various membrane receptors, including EGFR, CD44, VEGF and integrins, thereby promoting cancer metastasis." (PMID 32862200, 2020). "CD44 is also the most specific biomarker for the detection and isolation of oncogenic and chemoresistive cancer stem cells in noncardiac GC." (PMID 32908877, 2020). "In cancer cells with high levels of p‐TFCP2L1, CDK1, SALL4, and CD44 levels were significantly higher than in cells with low expression of p‐TFCP2L1, suggesting that a subset of p‐TFCP2L1‐positive cells could represent a population of bladder CSCs." (PMID 31709755, 2020). "Other signaling pathways contributing to PH pathology, including TGFβ-smad signaling, TNFα-NFkB signaling, IL661,62, and CD44-LOX signaling are known to induce Twist1 expression in cancer cells and may be involved in the mechanism." (PMID 32371931, 2020). "Cancer cells undergoing epithelial to mesenchymal transition (EMT), one of the major mechanism by which cancer cells become metastatic, show an increased expression of CD44 as well as a switch from CD44s to CD44v." (PMID 33143085, 2020).
cancer (continued). "In addition, we detected the mRNA expression of cancer stem cell makers, including c-MYC, CD44 and CD133, and found that their expression were increased in TRIP6-transduced ZR-75-30 and MDA-MB-231 cells but were decreased in TRIP6-silenced cells." (PMID 32082081, 2020). "Cancer stem cell (CSC), stem cell population in cancer, is detected with markers such as CD44, while the distinct markers for CSC have not been determined, so far." (PMID 32625096, 2020). "Furthermore, CD44 can interact with MMP-9, providing the cancer cell with enhanced invasion potential." (PMID 32527062, 2020). "Moreover, the relative expression of LINC00963 was consistently increased in sphere cells, CD44+, and ALDH1+ cells derived from two types of OSCC cell lines (SAS and GNM), suggesting that LINC00963 was also elevated in CSCs and may be associated with the cancer aggressiveness." (PMID 32357409, 2020). "These carcinomas expressed tdTomato, confirming their allograft origin, and characterized by predominant CD44 expression and absence of Lgr5 expression." (PMID 31901081, 2020). "In our study, CD44 and MMP7 were both upregulated in our cancer-normal comparisons." (PMID 31211760, 2019). "The CD44+/CD90+ cell population expressed n-cadherin, which is known as an essential component of the epithelial-mesenchymal transition state in CSCs and suggests that high levels of mEAK-7 in cancer cells are more likely to metastasize." (PMID 31288154, 2019). "Additionally, we also observed an up-regulation in some cancer stem cell markers such as NANOG, ABCC2, ABCC5, CD44 and KLF450,51." (PMID 31597943, 2019). "Studies have shown that CD44 and ICAM1 are cancer stem cell markers in ESCC." (PMID 31438645, 2019). "Importantly, shNEAT1 reduced stem cell populations such as CD44+/CD24−, ALDH+, and SOX2+, implicating that NEAT1 was closely related to cancer stemness in TNBC." (PMID 30894512, 2019). "Tumors had no significant change in cancer stem cell enrichment marker CD44+CD24−, but tumors from the obASC group showed decreased expression of CD326 (epithelial cell adhesion molecule)." (PMID 31118047, 2019). "In the analysis of cancer stem cells marker, we found that the combination GSK461364 plus docetaxel decreased the number of CD44+/CD24-/dim in SUM149 (from 26% in DMSO to 18% after treatment) and SUM159 (from 89% in DMSO to 77% after treatment) compared to control (DMSO)." (PMID 31751384, 2019). "Our group has recently experienced the ability of DCA to reduce the expression of cancer stem cell markers CD24/CD44/EPCAM in a pancreatic cancer cell line as well as to compromise spheroid formation and viability, further corroborating data obtained in other cancer models." (PMID 31827705, 2019). "Due to the correlation between PLOD2 and CD44/CD133 expression, PLOD2 might contribute to increasing cancer cell-like characteristics in LSCC." (PMID 31455288, 2019). "Consistently, cancer stemness markers CD133, CD44, and OCT4 were obviously increased in SW480CAFs-exos, SW620CAFs-exos and LOVOCAFs-exos cells by real-time PCR, western blot and immunofluorescence assays, indicating the enhancement of CRC cell stemness phenotypes by CAFs-exos." (PMID 31064356, 2019). "For example, CD44, a non-kinase transmembrane single-chained glycoprotein, is overexpressed in several cell types including cancer stem cells." (PMID 31013960, 2019). "We observed distinct features of cancer stem cells including CD133/CD44 dual positive cells and migration in SMG which was not altered by autophagy induction or inhibition." (PMID 31337825, 2019). "Knockdown of CD44 or CD147 has previously been shown to decrease proliferation and invasion of docetaxel-resistant PC-3M-luc PCa cells, as well as suppressed tumorigenesis and cancer metastasis of PC-3M-luc cells in xenograft model." (PMID 30935014, 2019).
cancer (continued). "These cells,named tumor initiating cells or cancer stem cells (CSCs),could generally be identified based on the expression of avariety of cell surface markers such as CD24, CD44, CD133,CD166, Trop-1 and EpCAM." (PMID 30825285, 2019). "Cytochrome c- and GrB-loaded hyaluronic acid nanogel could effectively target and release proteins to CD44-positive MCF-7 and A549 cancer cells, thereby yielding impactful antitumor effects." (PMID 30943985, 2019). "The results showed that YTHDF1 silencing formed smaller tumors.Then we validated the expression of CD133, CD44, ALDH1, OCT4, and Lgr5 in xenograft tumors by RT-qPCR, the results showed that YTHDF1 silencing downregulated the expression of CRC cancer stem cell markers in xenograft tumors." (PMID 31131257, 2019). "Moreover, we observed that inhibition of 5-Lox downregulates CD44, CD133, ALDH1 and ABCG2 which are characterized to be cancer stem cell- or tumorigenicity-markers in adult stem cells." (PMID 30728896, 2019). "In addition, and remarkably, OGT inhibition induced the appearance of a double positive CD44+/CD133+ cell subpopulation in both primary SW480 and metastatic SW620 cancer cell lines." (PMID 31139149, 2019). "In addition, CD24+CD44+ cells were found to be more chemoresistant and tumorigenic compared with CD24−CD44+ cancer cells." (PMID 31137841, 2019). "Furthermore, several surface markers such as CD90, CD44, CD133 were analyzed using flow cytometry to measure the cancer stem cell population." (PMID 31781559, 2019). "The expression intensity of CD44 on circulating MDSCs was also dim suggesting more immature phenotype, however, the percentage of CD44+MDSCs (irrespective of the CD44 marker intensity) was higher in the blood of mice with advanced cancer." (PMID 31881770, 2019). "For all of these events features of cancer cells such as their ability to adhere to various ECM and cell surface molecules (collagen, fibronectin, selectins, CD44, ICAM and vascular cell adhesion molecule) as well as increased mobility throughout the actively remodeled ECM are of special importance." (PMID 30637950, 2019). "In addition, the expression of Jagged-1 significantly correlated with the expression of BMP-4, EMT markers such as Slug, and cancer stem cell makers including ALDH and CD44." (PMID 31409851, 2019). "The CyTOF analysis revealed the emergence of CD11b+/Gr-1+/CD44+ or CD11b+/Gr-1+/IL-17A+ myeloid-derived suppressor cells (MDSCs) and the absence of B220+ or CD62L+ B-cells, the CD62L+/CD4+ and CD62L+/CD8+ T-cells in the spleen of advanced cancer." (PMID 31881770, 2019). "Moreover, the expression of cancer stem cell markers, CD133 and CD44, elevated in CSCcmBT549 cells when compared with those in miPSCs." (PMID 31905766, 2019). "In several cancers, TNF-α affected the epithelial-mesenchymal transition (EMT) and the expression of matrix metalloproteinase 9 and CD44, which may participate in the resistance of sunitinib therapy." (PMID 31462894, 2019). "Furthermore, identification of protein markers such as ALDH1A1, Sox2, CD44, Oct4, CD133, CD24, and Nanog, etc. have been vital in studying CSCs in cancer research." (PMID 31530793, 2019). "Among them, CD44 is highly expressed in HNSCC cancer stem cells and circulating cancer stem cells." (PMID 30875950, 2019). "The carcinoma with plasmacytoid morphology of the stomach presented, in our material, several negative prognostic factors: age over 50, advanced stage (both pTNM and Dukes-MAC like), angiolymphatic invasion, EMT phenotype, and positivity for c-MET and CD44." (PMID 31205468, 2019). "The immediately budded daughter cells from PGCCs show activated expression of cancer stem cell markers, including ALDH1a, CD133, and CD44, indicating that at least some cancer stem cells may be daughter cells that have immediately budded from PGCCs." (PMID 30040989, 2018).
cancer (continued). "In addition, mRNA expressions and protein levels of cancer stem markers aldehyde dehydrogenase-1 (ALDH1), cluster of differentiation 133 (CD133), CD44, Lgr5, and Musashi-1 were reduced after tumidulin treatment." (PMID 30441806, 2018). "In addition, CD44 and CD47, which we found to be upregulated after ADH1B upregulation, help in metastasis by promoting cancer cells’ adhesion to peritoneum." (PMID 29861857, 2018). "Although the T HT signal in vivo slightly increased in response to CD44 knockdown, in vivo and in vitro results were consistent: CD44 knockdown did not suppress amounts of HT in T or cultured cancer cells." (PMID 29674746, 2018). "Furthermore, during ethanol‐induced cellular transformation, cells gained the phenotypes of cancer stem cells (CSCs) by expressing pluripotency maintaining factors (Oct4, Sox2, cMyc and KLF4) and stem cell markers (CD24, CD44 and CD133)." (PMID 29761897, 2018). "Since self-renewal and aberrant differentiation are characteristic features of cancer stem cells, it became imperative to assess the synergistic effect of Silibinin+ 5FU on the clonogenic ability and migratory potential of HCT116 derived CD44+ subpopulation." (PMID 30451890, 2018). "HA interacts with multiple cell surface receptors, including CD44, receptor for hyaluronan mediated motility (RHAMM) and intracellular signaling pathways, including receptor tyrosine kinase pathways, to promote the survival and proliferation of cancer cells." (PMID 30513961, 2018). "CD44 is regarded as a marker of normal prostatic epithelium stem cells as well as cancer stem cells (CSCs) and CD44high PCa cells are more tumorigenic and metastatic than the isogenic CD44-negative (CD44neg) PCa cells." (PMID 30112117, 2018). "The routinely employed method of cancer stem cell identification is the sorting of BCSC-like cells by spherocyst medium followed by the isolation of the cancer stem cells according to their specific markers, such as CD133 and CD44." (PMID 29559853, 2018). "Compared to HER2 amplification in HER2-positive cancer cells, the increased levels of HER2 in the CD44+/CD24–/low BCSCs were relatively low because these changes may be associated with altered epigenetic regulation." (PMID 29464036, 2018). "We have reported that aldehyde dehydrogenase activity (termed ALDH+) and CD44+CD24− mark two largely non-overlapping populations of cancer stem cells, which have epithelial-like and mesenchymal-like phenotypes, respectively." (PMID 29606612, 2018). "Altered expression of CD44 from CD44v to CD44s induces EMT and promotes cancer progression." (PMID 30042817, 2018). "Furthermore, pharmacologic inhibition of glycolysis by addition of 2-deoxyglucose (2-DG) showed the most significant effect on increasing cytotoxic effects and decreasing expression of cancer stemness marker (OCT4 and CD44) in sphere cells." (PMID 29416012, 2018). "Furthermore, TNF-β induced a more pronounced cancer stem cell-like (CSC) phenotype (CD133, CD44, ALDH1) and resveratrol suppressed formation of CSC cells in two different CRC cells and this was accompanied with a significant increase in apoptosis (caspase-3)." (PMID 30002278, 2018). "Furthermore, while one would expect OCSC to represent a minor subpopulation of cancer cells, the prevalence of cells expressing putative CSC markers, such as CD44 and CD24, is often high in OC specimens." (PMID 28320418, 2017). "Among the best described sub-population of cancer cells generated by non-genetic mechanisms are cells characterized by a CD44+/CD24− cell surface marker profile." (PMID 28092266, 2017). "CD44 and LGR5 are the target genes of WNT signaling pathway and mark CSCs and normal intestinal stem cells, suggesting that upregulation of WNT signaling pathways is important for both normal and cancer stem cells in the intestine." (PMID 29064439, 2017).
cancer (continued). "The expression of previously-reported candidate marker genes, such as CD133, CD44 and ABCG2, which are argued to be related to cancer stem cells, and the transduced genes OCT3/4, SOX2 and KLF4 were not significantly different among the parental A549, OSK-A549-Colony and OSK-A549-SN cells." (PMID 28951614, 2017). "CD44 and CD133 are the most common CSC markers and broadly expressed on cancer cells." (PMID 27244887, 2017). "Moreover, NK cells preferentially eliminate CD24+/CD44+, CD133+ and ALDHbright CSCs in variety of human cancer cell lines through upregulation of NKG2D ligands." (PMID 28137308, 2017). "Moreover, CRC7.4 had high-level expression of CD133, a cancer stem cell (CSC) marker, as well as other CSC markers such as CD44 and EpCAM." (PMID 29173894, 2017). "Therefore, we checked the expression of CD44 and CD133 in cancer cells in tumors after treatment with 0.9% saline, empty micelles, curcumin or CPM in vivo." (PMID 28956452, 2017). "In addition, the levels of cancer stem cell markers, such as aldehyde dehydrogenase-1, cluster of differentiation 133 (CD133), CD44, Lgr5, Musashi-1, Ephrin receptor, and Bmi-1 increased after exposure to BP compounds." (PMID 28862656, 2017). "CD44, ABCG2, Oct3/4, Nanog are frequently used as makers for cancer stem cells." (PMID 28076853, 2017). "Interestingly, several previously identified EOC cancer stem cell (CSC) markers, including CD44, CD24, CD117 (Kit), and EpCAM, were up-regulated in ID8-P1 vs. ID8-P0 cells." (PMID 29163813, 2017). "We found that metformin reduced the RNA expression of two colorectal CSC markers involved in Wnt signalling, CD44 and LGR5, thus confirming that it may affect cancer cells with “stem” characteristics." (PMID 29167573, 2017). "We found that high CD44/CD24 ratio and ALDH1+ were related to cancer malignancy." (PMID 29062075, 2017). "As an example, the cancer stem-like cell population of LS174T cells expresses the CD44 glycoform, and does not express CD133." (PMID 29100290, 2017). "CSCs display surface markers, including CD44 and CD133, in various cancer types." (PMID 27244887, 2017). "Hyaluronan–CD44 interaction up-regulates EMMPRIN, a molecule belonging to the Ig superfamily present on the plasma membrane of normal and cancer cells and induces breast epithelial cell invasiveness by promoting EGFR signalling and assembly with EGFR and CD44 in lipid raft like domains." (PMID 28465354, 2017). "In a previous work, we developed a Cyt c-HA based DDS which showed systemic selectivity towards CD44-positive cancer cells when compared to CD44-negative normal cells." (PMID 28706754, 2017). "To clarify whether polyploid cells or their progeny exhibit cancer stem cell-like properties, we analyzed the numbers of CD24, CD44 and CD133 positive cells, using H33342 staining as a ploidy discriminator." (PMID 28030837, 2017). "KRT23 promoted cancer stem cell properties and increased the expression of CD133 and CD44." (PMID 28749462, 2017). "Moreover, treatment with siRNA-SMAD5 induced a luminal CD44-/CD24+ phenotype in MDA-MB 231 cells, indicating that SMAD5 expression is required to maintain a CD44+/CD24- cancer stem cell-like phenotype." (PMID 29207686, 2017). "As the CD44+/CD24− population can identify both CSC and early progenitor cells, we also stained HOXC8-expressing cancer cells with the PKH26 dye and studied the ability of HOXC8 to regulated the more primitive and quiescent CSC population which is able to retain the dye upon cell proliferation." (PMID 28202042, 2017). "Although the exact mechanism whereby CD44+ cancer cells stimulate OPN secretion is not clear, this study suggests that, despite strongly relying on their niche, CSCs can reprogram stromal cells (e.g., TAMs) so that the latter can gain a growth advantage." (PMID 28769537, 2017). "Indeed, CD44 and the B-cell-specific Moloney murine leukemia virus insertion site 1 (BMI1) support the stem cell state in both cancer cells and embryonic stem cells." (PMID 29123181, 2017).